ENSG00000284686 (novel transcript)
Gene: Protein-coding gene on chromosome 1 (56,173,433 to 56,524,495, reverse strand). Ensembl gene ENSG00000284686.
Genetic constraint (gnomAD): Missense variants: 172 observed, 257.16 expected, observed/expected ratio (o/e) 0.67, 90% interval 0.59 to 0.76. Synonymous variants: 83 observed, 95.92 expected, observed/expected ratio (o/e) 0.87, 90% interval 0.72 to 1.04.